PARP9 (poly(ADP-ribose) polymerase family member 9)
Diseases named in the same sentence as PARP9 in open-access papers (continued):
Sharing a sentence is not in itself a finding about the gene and the disease.
acute myeloid leukemia (1 paper, 2021). Acute myeloid leukemia (AML) is a group of neoplasms arising from precursor cells committed to the myeloid cell-line differentiation. "High expression of PARP9 is associated with poor survival in acute myeloid leukemia (AML) patients." (PMID 34976832, 2021).
arterial disease (1 paper, 2016). "According to the network analysis that linked PARP9 and PARP14 with arterial disease, we performed immunohistochemistry in arterial lesions." (PMID 27796300, 2016). "Seeking additional in vivo evidence for the potential role of PARP9 and PARP14 in arterial disease involved immunohistochemical analysis of human carotid atherosclerotic plaques surgically removed by endarterectomy." (PMID 27796300, 2016).
B-cell lymphomas (1 paper, 2014). "Indeed, after the initial discovery that PARP9 was highly expressed in aggressive B-cell lymphomas, PARP9 and 14 were shown to regulate expression of several immunity-related genes." (PMID 24875882, 2014).
cardiac arrhythmia (1 paper, 2024). Any disturbances of the normal rhythmic beating of the heart or MYOCARDIAL CONTRACTION. "Investigating the impact of poly (ADP-ribose) polymerase 9 (PARP9) on Angiotensin II (Ang II)-induced fibroblast activation and the therapeutic effects of pirfenidone (PFD) offers valuable insights into cardiac arrhythmias." (PMID 39213416, 2024).
cardiomyopathy (1 paper, 2025). A disease of the heart muscle or myocardium proper. "Therefore, TRIM29, TRIM18, and PARP9 may regulate ferroptosis to manage cardiomyopathy." (PMID 40356926, 2025).
colorectal cancer (1 paper, 2025). A primary or metastatic malignant neoplasm that affects the colon or rectum. "We previously discovered that the multifractionated dose IR upregulated the expression of unconventional PARP family members including PARP9, PARP12, PARP13 and PARP14 in colorectal cancer cells grown in laminin-rich ECM 3D cell culture." (PMID 40646573, 2025). "The expression of PARP9, PARP12, PARP13 and PARP14 was particularly elevated in irradiated colorectal cancer HT29 cells in a microenvironment-dependent manner." (PMID 40646573, 2025). "This indicates that PARP13 may indirectly modulate treatment response by regulating PARP9 and PARP14 related pathways, emphasizing the necessity for further investigation of PARPs in colorectal cancer." (PMID 40646573, 2025).
fibrosis (1 paper, 2024). the formation of excess fibrous connective tissue in an organ or tissue in a reparative or reactive process. "New insights into cardiac fibrosis emerged from the notable connection between PARP9, immunological regulation, and fibrotic transformation." (PMID 39213416, 2024).
HIV-1 infection (1 paper, 2020). The type species of lentivirus and the etiologic agent of acquired immunodeficiency syndrome (AIDS). "For the validation of the gene expression results and to confirm that the higher expression of these molecules was associated with uncontrolled HIV-1 infection, mRNA levels for PARP9, MX1 and USP18 were validated in independent cohorts of HIV-1 infected individuals." (PMID 32760119, 2020). "The identified three genes play all a role in the interferon-mediated antiviral response: PARP9 is increased in vitro models of HIV-1 infection and, together with DTX3L, can target histone H2BJ and increase the expression of interferon stimulated genes (ISGs)." (PMID 32760119, 2020).
multiple sclerosis (1 paper, 2025). A progressive autoimmune disorder affecting the central nervous system resulting in demyelination. "The disease-specific pathway of multiple sclerosis (MS) signaling was upregulated across all YWH groups, marked by shared upregulation of interferon-responsive genes such as PARP9 and PARP14, indicating persistent immune activation despite viral suppression." (PMID 40862746, 2025).
rectal cancer (1 paper, 2025). A primary or metastatic malignant neoplasm that affects the rectum. "We then explored the distribution of low and high fold of expression after CRT of PARP9, PARP12, PARP13, and PARP14 in both tumor and adjacent normal tissue sample groups from rectal cancer patients." (PMID 40646573, 2025). "The high pre-treatment PARP9 levels and a blunted post-treatment increase in both PARP9 and PARP14 expression emerged as independent predictors of poorer overall survival in rectal cancer patients." (PMID 40646573, 2025). "Surprisingly, our findings highlighted the potential clinical significance of PARP9 and PARP14 in rectal cancer." (PMID 40646573, 2025). "Overall, these findings suggest that PARP9 and PARP14 expression profiles could be important prognostic factors for survival in rectal cancer patients." (PMID 40646573, 2025). "Elevated pre-treatment PARP9 expression levels and a blunted post-treatment increase in PARP9 and PARP14 expression predicted poor overall survival in rectal cancer patients, while PARP13 emerged as the most significant discriminator between tumor and healthy tissue." (PMID 40646573, 2025). "Notably, high pre-treatment PARP9 expression and a weaker post-treatment increase in PARP9 and PARP14 expression emerged as independent predictors of worse overall survival in rectal cancer patients." (PMID 40646573, 2025).
rectal tumors (1 paper, 2025). "Taken together, this study demonstrates that CRT significantly increases the expression of PARP9, PARP12, PARP13 and PARP14, specifically in rectal tumor tissue." (PMID 40646573, 2025). "Finally, we demonstrated that chemoradiotherapy significantly upregulates the expression of PARP9, PARP12, PARP13 and PARP14 exclusively within rectal tumor tissues." (PMID 40646573, 2025).
retinal degeneration (1 paper, 2017). Degeneration of the retina. "Our transcriptomic data also revealed an increase in a number of non-apoptotic pathway genes that have been implicated in retinal degeneration, such as a number of poly-ADP-ribose-polymerases (PARP9, PARP14, PARP15) and histone deacetylases (HDAC7, HDAC10, HDAC11)." (PMID 29263354, 2017).
Stroke (1 paper, 2025). Sudden impairment of blood flow to a part of the brain due to occlusion or rupture of an artery to the brain. "Machine learning technique, LASSO regression analysis, was utilized to refine our search, leading to the identification of three genes, EIF2AK2, PARP9, and IFI27, which demonstrated strong diagnostic potential confirmed by ROC curves in both stroke and SLE cohorts." (PMID 40313968, 2025). "In the stroke validation set (GSE58294), the AUC values for EIF2AK2, PARP9, and IFI27 were 0.761, 0.689, and 0.584, respectively." (PMID 40313968, 2025). "The correlation analysis indicated an inverse relationship between the genes EIF2AK2, PARP9, and IFI27 and the presence of M2 macrophages within the stroke dataset." (PMID 40313968, 2025). "This study marks the first exploration of hub genes in the context of stroke and SLE, suggesting EIF2AK2, PARP9, and IFI27 as potential biomarkers for further investigation into the mechanistic underpinnings of their comorbidity." (PMID 40313968, 2025). "In the stroke-GSE16561 dataset, the AUC values for EIF2AK2, PARP9, and IFI27 were 0.862, 0.797, and 0.685, respectively, all exceeding 0.6." (PMID 40313968, 2025). "Together, these hub genes (EIF2AK2, PARP9, and IFI27) are integral to the regulation of autoimmune and inflammatory responses, representing potential biomarkers for SLE with concomitant stroke." (PMID 40313968, 2025). "Therefore, we validated EIF2AK2, PARP 9 and IFI 27 as hub genes in the progression of stroke." (PMID 40313968, 2025). "The results showed that the expression of EIF2AK2, PARP 9 and IFI 27 was consistent with our DEGs analysis, and the gene expression was increased in stroke mice compared with non-infarcted area." (PMID 40313968, 2025).
viral myocarditis (1 paper, 2025). Myocarditis that is caused by an infection with a viral agent. "Similarly, PARP9 (poly (ADP-ribose) polymerase 9) manages viral myocarditis by engaging the PI3K/AKT pathway to drive type I interferon responses." (PMID 40356926, 2025).
tumor (25 papers, 2014 to 2026). "PARP9 is abnormally expressed in a variety of tumors and is associated with tumor cell apoptosis and DNA damage." (PMID 39739965, 2024). "The proteins encoded by PARP14 and PARP9 are DNA damage repair enzymes that act as tumor suppressors by consuming NAD+ to stabilize cell metabolism and prevent genomic instability from containing potential oncogenic mutations." (PMID 38186577, 2023). "In the multivariate analysis, high PARP9 expression in patients was independently associated with overall survival (HR = 1.04, 95% CI 1.01‐1.07, P = .009), together with tumor status (HR = 23.64, 95% CI 3.29‐169.85, P = .002) and histological type (HR = 2.02, 95% CI 1.63‐2.49, P < .001)." (PMID 32678519, 2020). "Our results demonstrated that PARP9 knockdown significantly inhibited tumorigenesis in PC xenograft models compared with control groups, whereas PARP9 overexpression conversely promoted tumor growth." (PMID 41357999, 2025). "Remarkably, LOXL2 overexpression in PARP9 knockdown cells significantly attenuated apoptosis and enhanced resistance to DNA damage, partially reversing the tumor-suppressive effects of PARP9 knockdown." (PMID 41357999, 2025). "Much attention has been given to pro-tumour roles of PARP9 and PARP14 in a variety of cancer types, particularly as some tumours have elevated levels of expression of transcript and protein." (PMID 38182103, 2024). "Gene expression profiling confirmed increased expression levels of other members of the ARTD family including Parp9, Parp10, Parp12 and Parp14 in Parp7KO tumours." (PMID 39867896, 2024). "More recently, PARP14 protein levels were found to be increased in HNSC and other tumour types, along with elevated protein levels of its interactors PARP9 and DTX3L." (PMID 39189367, 2024). "The genes upregulated in MΦ subtypes from tumours treated with topical caerin gel including Stat2, Isg15, Tap1, Psmb9, and Parp9, were more highly expressed in the CCI than CCII MΦs." (PMID 36497272, 2022). "In addition to cellular experiments, we established subcutaneous xenograft tumor models in nude mice using human PC cells with PARP9 knockdown or overexpression." (PMID 41357999, 2025). "Systematic integration of existing knowledge about PARP9’s roles in other tumor types and functional elucidation in PC may reveal novel therapeutic targets for this disease." (PMID 41357999, 2025). "Many downregulated genes in tumour‐infiltrating peripheral CD8+ T cells are associated with classical IFN responses (IFI6, IFI27, MX1, STAT1, EPSTI1 PARP9, ISG15), cell proliferation (STMN1, CENPF, HELLS, NUSAP1, and DNPH1), and T cell costimulation (CD28, TMIGD2, TNFRSF4, CD27, and TNFRSF18)." (PMID 39350478, 2024). "We investigated the relationship between the expression of PARP9 and six immune cells that frequently infiltrate the tumor, including CD8+T cells, natural killer (NK) cells, tumor‐associated macrophages (TAMs), regulatory T cells (Tregs), myeloid‐derived suppressor cells (MDSCs), and neutrophils." (PMID 32678519, 2020). "Based on our network and the ceRNA mechanism, we speculated that LINC01128 might act as a tumor suppressor in MM through multiple mechanisms, including miR-142-5p/PARP9 or FAM133A axis, and the miR-299-3p/estrogen-related receptor gamma axis." (PMID 33193574, 2020). "PARP9 expression was significantly related to age (P < .001), tumor grade (P < .001), histological type (P < .001), IDH mutation (P < .001), KPS (P = .05), tumor status (P < .001), and vital status (P < .001)." (PMID 32678519, 2020). "Therefore, a combined targeted inhibition of STAT1, PARP9, PARP14 and/or DTX3L could increase the efficacy of currently available treatment for prostate, DLBCL and other high-risk tumour types harbouring an increased STAT1 signalling." (PMID 39189367, 2024). "Mechanistically, abundant cytokines (TNF-α, FGF) in the IE tumor microenvironment promote FASN and PARP9 expression." (PMID 41969226, 2026).
tumor (continued). "In PC subsets, IFNβ-induced upregulation of NAD + -consuming enzymes PARP9, PARP10, and PARP14 enhances tumor sensitivity to nicotinamide phosphoribosyltransferase inhibitors." (PMID 41357999, 2025). "The analysis of OS in patients, stratified by changes in PARPs expression in tumor tissue induced by CRT, revealed a worse survival prognosis when there is a lower change in PARP9 and PARP14 expression (p = 0.025 in both cases)." (PMID 40646573, 2025). "Moreover, PARP9 expression positively correlates with metastasis of axillary lymph node and is negatively associated with ER expression, as well as PSMB8 and PSMB9 and immunoproteasomes, which induce tumor angiogenesis via VEGF-A and are overexpressed in most cancers, including BC." (PMID 36766731, 2023). "Initially, an online database was utilized to assess mRNA expression levels of PARP9 across different tumor types, followed by an analysis of its expression in TCGA-STAD, ultimately revealing that elevated PARP9 levels correlate with poor prognosis in GC patients." (PMID 39739965, 2024). "PARP9 had a high concordance with prominent immune checkpoint molecules, including PD‐1, PD‐L1, B7‐H3, and TIM‐3, suggesting their synergistic roles in regulating the immune response within the tumor microenvironment." (PMID 32678519, 2020). "Our initial aim was to explore the expression of pro-tumour ADP-ribosyltransferases PARP14 and PARP9/DTX3L particularly in HNSCC, which are characteristically resistant to treatment and PARP9/14 mediated survival might represent a mechanism for increased survival." (PMID 38182103, 2024). "The mRNA levels of TGM2, USP18, DDX58, PARP9, STAT1 and STAT2 were not significantly different between ER--tumor tissues and their corresponding tumor-adjacent tissues." (PMID 29416786, 2018).
infection (20 papers, 2016 to 2026). The state of being infected such as from the introduction of a foreign agent such as serum, vaccine, antigenic substance or organism. "This is further supported in our PARP9 KO mice, where deletion of PARP9 in vivo rendered the PARP9 KO mice highly susceptible to infections with RNA viruses (e.g., VSV and reovirus) due to impaired type I IFN production in vivo." (PMID 33976210, 2021). "In TB, PARP9 is significantly upregulated and associated with an increased risk of infection." (PMID 40565608, 2025). "Furthermore, mice deficient for PARP9 show enhanced susceptibility to infections with RNA viruses because of the impaired type I IFN production." (PMID 33976210, 2021). "Coincident with increased lung M. tuberculosis CFU, Parp9–/– mice also exhibited enhanced inflammation with infection." (PMID 37200107, 2023). "We detected increased M. tuberculosis CFU in the spleen at early (21 and 60 days post infection [dpi]) and late (100 dpi) time points in Parp9–/– mice." (PMID 37200107, 2023). "We found members of this family upregulated by both VN1203 and BC500 infection in ducks (PARP9, PARP10, PARP12 and PARP14)." (PMID 34804075, 2021). "To further elucidate the importance of PARP9 in vivo in mediating host defense against infection by RNA viruses, we first intraperitoneally infected both WT and PARP9 KO mice with the RNA virus VSV and monitored survival over time." (PMID 33976210, 2021). "Expression of Parp1 mRNA changed little, but mRNAs for Parp9, -10, -12, -13, and -14 were increased by infection." (PMID 32047134, 2020). "At 2 days after infection, the brain levels of Parp9, -10, -12, -13, and -14 mRNAs and the spinal cord levels of Parp14 mRNA were higher in Y114A-infected mice than in either WT or G32S-infected mice." (PMID 32047134, 2020). "However, the BMDC or BMDM from WT and PARP9 KO mice were comparable in terms of the proinflammatory cytokine IL-6 after infection by those RNA viruses." (PMID 33976210, 2021). "To further identify the physiological RNA species recognized and bound by PARP9 during infection with RNA virus reovirus, we purified the RNAs that immunoprecipitated together with anti-PARP9 in WT and PARP9 KO BMDC left infected (Mock) or infected with reovirus." (PMID 33976210, 2021). "Similarly, compared with those cells expressing control vector, there were dramatically more IFN-α and IFN-β production by PARP9 KO BMDC or BMDM overexpressing PARP9 after infection by RNA viruses." (PMID 33976210, 2021). "Although studies have not clearly determined whether PARP9 directly binds to dsRNA produced by IAV and vesicular stomatitis virus (VSV), infection can activate the same signaling pathway induced by PARP9, which in turn promotes the production of type I interferon." (PMID 41460301, 2025). "Despite inter-individual variability and cohort heterogeneity, our findings regarding four DMPs (IFI44L, MX1, DDX60, and RABGAP1L) and two DMRs (PARP9 and GNA12) replicate changes described both in the acute phase of infection and at long-term follow-up." (PMID 42288901, 2026). "Compared with WT BMDC, PARP9 KO BMDC produced two- to sixfold less type I IFN at 12 h or 16 h post-infection by reovirus, VSV or Flu virus." (PMID 33976210, 2021). "Further studies are necessary to ascertain mechanisms of PARP-9 in viral replication and the potential impact of PARP-9 activation during infection." (PMID 34485381, 2021). "Expression of the remaining four genes (PARP9, SP110, SP100 and PRIC285) was unchanged by infection." (PMID 27533247, 2016). "This suggests that PARP9 may activate the antiviral signaling pathway by directly binding to the dsRNA of IAV and VSV, or by other indirect mechanisms, in response to infection with these viruses which warrants further studies." (PMID 41460301, 2025).
infection (continued). "The reduction of PARP9 combined with the reduction of NK and CD8+ cells leads to a weak viral response of the host, which may be an important reason for the life-threatening severe infections in patients." (PMID 36212830, 2022). "Similarly, PARP9 KO BMDM produced two- to fivefold less type I IFN than WT BMDM at 8 h, 12 h or 16 h post-infection by those RNA viruses." (PMID 33976210, 2021). "For example, SARS-CoV2 induces expression of several noncanonical PARPs – PARP-7, PARP-9, PARP-10, PARP-11, PARP-12, PARP-13 and PARP-14 were substantially upregulated following infection with the magnitude of subsequent NAD+ depletion being proportional with viral titres." (PMID 34485381, 2021).